EGFR (epidermal growth factor receptor)
Diseases named in the same sentence as EGFR in open-access papers (continued):
Sharing a sentence is not in itself a finding about the gene and the disease.
Lymphadenopathy (6 papers, 2015 to 2025). Enlargement (swelling) of a lymph node. "In contrast, lymphadenopathy was more frequently associated with the EGFR 19Del mutation (OR = 0.462, P = 0.019; 95% CI: 0.242–0.881)." (PMID 41049833, 2025). "Conversely, lymphadenopathy was more frequently observed in the EGFR 19Del mutation group (P < 0.05)." (PMID 41049833, 2025). "Furthermore, compared to patients with EGFR mutations, lymphadenopathy was more common and remarkable in patients with EML4-ALK gene fusions in our study." (PMID 26332764, 2015). "KRAS-positive patients and ALK-positive were more likely to have lymphadenopathy, compared to EGFR-positive patients (p = 0.079 and p = 0.003, respectively)." (PMID 27518729, 2016). "In conclusion, EGFR mutations were associated with ground-glass opacity, KRAS-positive tumors were generally solid and less likely to metastasize to the lung and pleura, and ALK-positive tumors tended to present with lymphadenopathy, extranodal invasion, and lymphangitis." (PMID 27518729, 2016). "Lymphadenopathy was significantly more common among ALK-positive patients, compared to EGFR-positive patients (p = 0.003)." (PMID 27518729, 2016).
malaria (6 papers, 2021 to 2024). Malaria is a serious and sometimes fatal disease caused by a parasite that commonly infects a certain type of mosquito which feeds on humans. "As a malaria drug, chloroquine (CQ) can affect the function of the endolysosomal system and impair the endocytosis-mediated degradation of EGFR." (PMID 34884765, 2021). "The major signaling pathways enriched were “Malaria” (p = 3.38E−07), “EGFR tyrosine kinase inhibitor resistance” (p = 6.07E−07), “HIF-1 ” (p = 6.67E−07), “Focal adhesion” (p = 1.55E−05), and “African trypanosomiasis” (p = 1.87E−05) involving 7, 8, 9, 10, and 5 text mining genes, respectively." (PMID 38591204, 2024). "As malaria plasma sEVs had reduced levels of HBEGF and EGFR compared to healthy controls, endothelial cell activation might not happen via host sEVs in malaria patients." (PMID 36961624, 2023). "Furthermore, Proguanil, an anti-malaria drug that targets DHFR, has been suggested to play a role in preventing some cancers by enhancing EGFR degradation and inhibiting its downstream signaling pathway to induce autophagy 52,53." (PMID 37737478, 2023).
myeloid leukemia (6 papers, 2008 to 2025). A clonal proliferation of myeloid cells and their precursors in the bone marrow, peripheral blood, and spleen. "We have presented a literature overview of NDDS design strategies for targeting myeloid leukemia and EGFR/CD44-positive solid tumors." (PMID 33981532, 2021). "This article will focus on novel design strategies for nanoscale drug delivery systems, based on the unique molecular signatures of myeloid leukemia and EGFR/CD44-positive solid tumors, and the impact of novel discoveries in molecular tumor profiles on future chemotherapeutic protocols." (PMID 33981532, 2021).
myeloproliferative neoplasm (6 papers, 2013 to 2022). A clonal hematopoietic stem cell disorder, characterized by proliferation in the bone marrow of one or more of the myeloid (i.e., granulocytic, erythroid, megakaryocytic, and mast cell) lineages. "Somatic mutations affecting other ERBB and related receptor tyrosine kinases are observed in myeloproliferative neoplasms (MPN), and we show elevated EGFR levels in MPN samples, consistent with previous reports." (PMID 28550306, 2017).
oligoastrocytoma (6 papers, 2013 to 2023). A WHO grade II tumor composed of a conspicuous mixture of two distinct neoplastic cell types morphologically resembling the tumor cells in oligodendroglioma and diffuse astrocytoma. "In oligoastrocytomas, WHO grade II (one of four cases, 25%) but not WHO grade III tumors showed EGFR gene amplification." (PMID 24083241, 2013).
oropharyngeal tumors (6 papers, 2012 to 2024). "While it has been demonstrated that HPV-positive oropharyngeal tumors are associated with improved outcomes, it is unknown if anti-EGFR therapy is optimal for either HPV-positive or HPV-negative patients." (PMID 23150825, 2012). "HPV-positive oropharyngeal tumors tend to present decreased EGFR expression, and increased EGFR gene copy number is restricted to HPV-negative cancer." (PMID 27556186, 2016). "When sequenced FFPE tumors were projected onto tumor states and archetypes, tumors responsive to treatment (purple) clustered in state T2, characterized by EGFR-p63/WNT and downregulation of EMT-ZEB1 and DNA Repair-MYC-E2F, and associated with HPV-positive oropharyngeal tumors." (PMID 38505587, 2024). "We would speculate that the opposite effect also takes place, i.e., under RT tumors with high EGFR expression, such as oropharynx tumors, may become even more EGFR-addicted." (PMID 23637683, 2013).
papillary adenocarcinoma (6 papers, 2013 to 2026). A morphologic variant of adenocarcinoma. "Anti-Yo antibody was positive, and transbronchial biopsy confirmed papillary adenocarcinoma with EGFR exon 21 L858R mutation." (PMID 42022512, 2026). "In our preclinical studies, EGFR TKIs and/or an antibody against EGFR were effective against aggressive papillary adenocarcinomas that were located into the tympanic cavity and bulla, which correlated with inhibition of EGFR." (PMID 26027747, 2015).
pleural mesothelioma (6 papers, 2010 to 2023). A neoplasm that arises from the mesothelial cells of the pleura. "Overall, our findings are in agreement with evidence obtained in pleural mesothelioma cell lines that displayed co-activation of EGFR, Axl, and MET, supporting the hypothesis of a higher responsiveness to combined targeted therapies." (PMID 31752449, 2019). "Erlotinib and gefitinib are first-generation tyrosine-kinase inhibitors aimed at targeting the epidermal growth factor receptor (EGFR), which is over-expressed more in MPM than pleural mesothelioma." (PMID 37835398, 2023). "Strikingly, VEGF along with multiple RTKs essential for VEGF-mediated angiogenesis, including epidermal growth factor receptor (EGFR), MET, and AXL, are activated in pleural mesothelioma cell lines and tumors." (PMID 28191281, 2016).
radiation dermatitis (6 papers, 2008 to 2023). "Conventional chemotherapeutic agents and anticancer therapies featuring EGFR inhibitors increase the risk of severe radiation dermatitis." (PMID 30665451, 2019). "Based on the grade of the skin toxicity, treatment is adapted to the recommendations for EGFR-related rashes and radiation dermatitis." (PMID 18226196, 2008).
Renal cyst (6 papers, 2012 to 2023). A fluid filled sac in the kidney. "The inhibition of EGFR activity through genetic strategies or the use of tyrosine kinase inhibitors reduce renal cyst formation and enlargement in murine and human models of ADPKD." (PMID 33256255, 2020). "Expression of the EGFR, but not other EGFR-related receptors, was observed in renal cysts but was absent in non-ADPKD kidney tissue." (PMID 36914219, 2023). "The administration of EGFR tyrosine kinase inhibitor does not protect PCK rats from developing renal cysts, possibly due to an increased level of cAMP after treatment." (PMID 27891514, 2016). "In addition, an increased level of epidermal growth factor (EGF) receptor is demonstrated in renal cyst fluid, which is consistent with an overexpression of EGF receptor (EGFR) mRNA and protein in renal epithelia in cpk mice." (PMID 27891514, 2016).
seminoma (6 papers, 2011 to 2023). A radiosensitive malignant germ cell tumor found in the testis (especially undescended), and extragonadal sites (anterior mediastinum and pineal gland). "Analysis comparing the mutational status of genes with clinicopathologic data revealed that KIT (p = 0.007) was significantly mutated in seminomas, and EGFR (p = 0.010) in stage IS." (PMID 37007070, 2023). "For example the KITLG-IGFR/EGFR-Grb2-Sos-Raf-Ras-ERK path is specific to seminomas." (PMID 33251139, 2020). "However, CREB phosphorylation induction was still observed in scrambled siRNA, EGFR-targeted transfected cells, suggesting that EGFR is not required for M4 signaling in TCam-2 seminoma-derived cells (data not shown)." (PMID 23626723, 2013).
skin infection (6 papers, 2014 to 2023). An inflammatory process affecting the skin, caused by bacteria, viruses, parasites, or fungi. "It has been shown that therapeutic inhibition of the epidermal growth factor receptor (EGFR) is often associated with an increased occurrence of skin infections including infections with dermatophytes." (PMID 24747887, 2014). "Since patients receiving anti-cancer therapy by inhibition of the epidermal growth factor receptor (EGFR) often suffer from skin infections caused by S. aureus we additionally evaluated whether the EGFR pathway may be involved in the IL-1alpha and IL-1beta induction by S. aureus." (PMID 26808616, 2016). "For instance, inhibition of EGFR affects tissues normally dependent on EGF signals, causing skin dryness, acneiform rashes, and skin infections." (PMID 37686523, 2023). "This suggests that the EGFR plays an important role in cutaneous defense by its crucial role to mediate the expression of AMP such as RNase 7 and may offer an explanation for the increased susceptibility for skin infections of cancer patients receiving anti-EGFR therapy." (PMID 31749808, 2019).
skin papilloma (6 papers, 2010 to 2024). A benign papillary neoplastic growth on the skin composed of epithelial cells and a fibrous stalk. "The treatment of K14-HPV8E6 transgenic mice with Canertinib, an inhibitor of the RTK-activity of the EGFR, suppressed skin papilloma growth in response to UV-irradiation." (PMID 29176966, 2017). "Multiple applications of TPA, chrysarobin or okadaic acid result in increased tyrosine phosphorylation (activation) of EGFR and elevated levels of activated EGFR are found in skin papillomas." (PMID 21297902, 2010).
thymic tumors (6 papers, 2013 to 2024). "Alongside the infrequent occurrence of EGFR activating mutations and the presence of RAS mutations in thymic tumors, the limited responsiveness to EGFR inhibitors is well-accounted for." (PMID 38338833, 2024). "In 2020, a Meta-analysis study found that the expression of many markers was associated with higher Masaoka stage of thymic tumors, including EGFR, Glut-1, EMA, Bcl-2, etc.." (PMID 36797681, 2023). "Nevertheless, in the era of targeted therapy, there have been investigations into specific targets in thymic neoplasms which may improve response to therapy such as epidermal growth factor receptor (EGFR) mutations, c-kit mutations, and insulin-like growth factor-1R expression." (PMID 28116199, 2017). "Though several signaling pathways have been explored in thymic tumors, clinical trials with EGFR, KIT, VEGF, and IGF-1R, histone deacetylase, DNA methyltransferase, tropomyosin receptor kinase A, and, cyclin-dependent kinase inhibitors documented only modest clinical responses in advanced disease." (PMID 23765114, 2013). "Despite the best efforts to build preclinical and translational models to support the use of EGFR and KIT TKIs, these drugs ultimately showed limited activity across the spectrum of thymic tumors." (PMID 38254905, 2024). "For thymic tumors, EGFR protein overexpression did not correlate with histologic subtype, and discrepancies between protein expression and gene amplification were noted." (PMID 38254905, 2024).
thyroid (6 papers, 2013 to 2024). "This suggests that the relationship between miR-7-5p, IRS2 and EGFR may play a significant role in thyroid tumorigenesis." (PMID 34381564, 2021). "Two of these are EGFR (ERBB1) and ERBB4, which have not been previously reported to play a role in thyroid carcinogenesis." (PMID 29133385, 2018).
tylosis (6 papers, 2015 to 2021). "Gain-of-function (GOF) mutations in the human rhomboid 5 homolog 2 (RHBDF2) gene constitutively activate epidermal growth factor receptor (EGFR) signaling to cause tylosis with esophageal cancer syndrome (TOC; OMIM: 148500)." (PMID 30022999, 2018). "Together, these results, along with the recent findings that mutations in Rhbdf2 in mice result in enhanced EGFR pathway activation, suggest a possible mechanism for the association between RHBDF2 mutations and tylosis." (PMID 28655741, 2017). "Second, keratinocytes from tylosis patients show a wound-healing phenotype—accelerated proliferation and migration through constitutive activation of EGFR signaling." (PMID 29116018, 2017). "Collectively, our data suggest that RHBDF2 plays a critical role in regulating EGFR signaling and its downstream events, including development of tylosis, by facilitating enhanced secretion of AREG." (PMID 28655741, 2017). "The role of RHBDF2 in enhancing amphiregulin (AREG) secretion, and consequently activating the epidermal growth factor receptor (EGFR) pathway, has significance for the skin disease tylosis." (PMID 28655741, 2017). "Further, substantial evidence implicates the involvement of AREG-induced constitutive activation of the EGFR pathway in tylosis." (PMID 28655741, 2017). "It is likely that enhanced EGFR activity and TNFα shedding observed in tissue from patients with tylosis with oesophageal cancer facilitates tumourigenesis through aberrant and exaggerated wound healing, in response to stress within the oesophagus." (PMID 26419362, 2015). "In addition, skin biopsies of tylosis patients suggest increased EGFR activity." (PMID 28655741, 2017).
Ureteral obstruction (6 papers, 2013 to 2025). Obstruction of the flow of urine through the ureter. "Diminished EGFR expression and downstream intracellular signaling may thus be one of the underlying mechanisms responsible for attenuated tissue damage response to ureteral obstruction, contributing to the markedly reduced kidney fibrosis in 3F7-treated mice." (PMID 41318746, 2025). "Selective EGFR deletion in the fibroblast/pericyte population inhibits interstitial fibrosis in response to unilateral ureteral obstruction, ischemia or nephrotoxins." (PMID 37963889, 2023). "Furthermore, pharmacologic blockade of EGFR with gefitinib or erlotinib inhibits renal deterioration and fibrogensis induced by angiotensin II, unilateral ureteral obstruction (UUO) or 5/6 renal nephrectomy.." (PMID 23342059, 2013). "Expression of EGFR was elevated in interstitial myofibroblasts in human and mouse fibrotic kidneys and its selective deletion in the fibroblast/pericyte cells inhibited interstitial fibrosis resulting from unilateral ureteral obstruction, ischemia or nephrotoxins." (PMID 39234105, 2024). "A recent study of a unilateral ureteral obstruction (UUO) mouse, the expression of an E3 ubiquitin ligase called HUWE1 and EGFR was examined." (PMID 39234105, 2024). "PPI treatment inhibited stimulation of TGF-β1 signaling, activation of EGFR and STAT3, and decreased amount of renal epithelial cells arrested at the G2/M phase of the cell cycle after ureteral obstruction." (PMID 39234105, 2024).
Wilms tumor (6 papers, 2015 to 2023). An embryonal neoplasm characterized by the presence of epithelial, mesenchymal, and blastema components. "All Wilms tumor cell lines have a major activation of three tyrosine kinase receptors: EGFR, PDGFR and AXL, detected by their strong phosphorylation." (PMID 33379206, 2020). "The single case of EGFR KDD positive Wilms’ tumor in Gallant’s paper is also intriguing." (PMID 32490123, 2020). "Wilms’ tumors seem to be mostly negative for EGFR expression." (PMID 32490123, 2020). "To determine whether EGFR protein expression might be used as a surrogate marker to identify cases with EGFR KDD, we performed immunohistochemical staining on three CMNs harboring EGFR KDD, one CMN known to carry ETV6-NTRK3 fusion, two cases of CCSK, and three cases of Wilms’ tumor." (PMID 32490123, 2020). "In fact, no EGFR KDD was detected in 20 cases of CCSK and 208 cases of Wilms’ tumor in Wegert’s paper." (PMID 32490123, 2020).
airway hyperresponsiveness (5 papers, 2014 to 2026). "EGFR inhibition can also reduce eosinophil recruitment in the lungs as well as airway hyperresponsiveness." (PMID 24670222, 2014).
aneurysm (5 papers, 2017 to 2025). Bulging or ballooning in an area of an artery secondary to arterial wall weakening. "We analyzed anterior cerebral artery tissues by pathological and proteomic detection for the expression of p‐EGFR and relevant proteins, and vessel casting was used to evaluate the incidence of aneurysms in each group." (PMID 34729926, 2022). "Imatinib and erlotinib are 2 TKIs with different target receptors (c-abl and epidermal growth factor receptor, respectively) that have shown the capacity to attenuate experimental aneurysm growth in the murine AngII-induced aortic dissection model." (PMID 34185710, 2021). "Elevated expression of UBE4B may be caused by many miRNAs selected as biomarkers of AAA and lead to aneurysm expansion through inhibition of endothelial growth factor receptor (EGFR)-mediated proliferation of vascular cells by enhancing EGFR degradation." (PMID 32599769, 2020).
asthenia (5 papers, 2014 to 2023). Clinical sign or symptom manifested as debility, or lack or loss of strength and energy. "Of note, the incidence of grade ⩾3 asthenia (27.3%) was somewhat higher than generally reported in other studies of EGFR mAbs in combination with FOLFOX regimens." (PMID 26766738, 2016).
autism spectrum disorder (5 papers, 2017 to 2024). A spectrum of developmental disorders that includes autism, and Asperger syndrome. "However, differences were also observed as pathway proximity analysis revealed in addition the “PI3K/AKT signaling”, “oxytocin signaling”, “EGFR signaling” and “axon guidance” pathways, whose perturbations have already been described in autism spectrum disorders." (PMID 38102483, 2024).
brain glioma (5 papers, 2013 to 2025). A malignant glioma that involves the brain. "Several mutated genes specific to brain glioma have been found in exosomes, such as MGMT, PTEN, EGFR, and many others." (PMID 35448031, 2022). "EGFR has been shown to initiate brain gliomas with short latency in mice only when combined with multiple tumor suppressor losses, such as Cdkn2a and Pten." (PMID 32727536, 2020). "PTEN loss is a common event and known to cooperate with EGFR in brain gliomas but its role is unclear in spinal tumors, with no previous mouse models (to our knowledge) showing whether Pten drives spinal gliomas." (PMID 32727536, 2020).
bronchiectasis (5 papers, 2016 to 2024). Segmental, irreversible dilation of the bronchial tree resulting in the accumulation of secretions which leads to obstruction. "Of the 246 patients, 100 (41 %) had EGFR mutations in their specimens, and 22 (9 %) had chronic lung inflammatory diseases (16 with interstitial pneumonia, 3 with NTM infection, and 3 with bronchiectasis)." (PMID 27842505, 2016). "Traction bronchiectasis was also less frequently observed in the EGFR mutant group." (PMID 38783331, 2024).
bronchitis (5 papers, 2013 to 2025). An acute or chronic inflammatory process affecting the bronchi. "A novel association between bronchitis and an ERBB1/EGFR SNP rs2227983 was also identified and possible gene–gene interactions between MUC5AC and ERBB1 and IL1RN are described." (PMID 23551418, 2013). "A novel association between bronchitis and a non-synonymous functional ERBB1 SNP, rs2227983 (aka epidermal growth factor receptor:R497K, R521K) is also reported and evidence presented of interaction between MUC5AC and ERBB1 and between MUC5AC and IL1RN with respect to bronchitis." (PMID 23551418, 2013).